JAK2 (Janus kinase 2)
Diseases named in the same sentence as JAK2 in open-access papers (continued):
Sharing a sentence is not in itself a finding about the gene and the disease.
lymphoma (continued). "Ruxolitinib (JAK1/JAK2), Tofacitinib (JAK1/JAK3) and Ritlecitinib (JAK3 selective) were selected in the current study based on their clinical efficacies in treating lymphoma and autoimmune diseases." (PMID 35911775, 2022). "Abnormal activation of the JAK2/STATS signaling pathway is closely related to the occurrence and development of lymphoma." (PMID 34588425, 2021). "The amplification of this chromatin remodeler has been suggested, in addition, and in synergy to JAK2, to have a pro-oncogenic effect on HL, among others upregulating MYC expression in lymphoma cells." (PMID 33567641, 2021). "FISH analyses using BAC clones covering lymphoma breakpoints (BCL2, BCL6, BCL11A, CCND1, CCND3, IG-H/K/L, JAK2, LMO2, MYC, PAX5, REL) all tested normal, excluding rearrangements at these loci." (PMID 26599546, 2015). "DOK-1 usually decreases both JAK-2 and STAT-3/5 phosphorylation in lymphoma cells." (PMID 33333886, 2020). "Although JAK1/JAK2 inhibitors have been shown to inhibit growth of canine lymphoma cells and malignant mast cells in vitro, there is no published data regarding the effects of such JAK inhibitors on canine tumor cell lines derived from solid tumors." (PMID 31409327, 2019). "In lymphoid neoplasms, aberrations in 9p24.1 (PD-L1, PD-L2, and JAK2 locus), latent Epstein-Barr virus infection, PD-L1 3′-untranslated region disruption, and constitutive JAK-STAT pathway are known mechanisms to induce PD-L1 expression in lymphoma cells." (PMID 28482851, 2017). "DNA hypermethylation of SOCS1 is also frequently found in certain types of lymphomas and in myelodysplastic syndrome, which may result in enhanced STAT1 and Jak2 activity and hence cell proliferation." (PMID 28445952, 2017). "This suggests germline or somatic amplification of Jak2 is unlikely to contribute to initiation and maintenance of the Eμ-Myc lymphomas." (PMID 28262675, 2017). "We have previously demonstrated that JAK2 mutations are not the cause; however, there have been few reports on the role of STAT3 mutations in lymphoma in general and specifically DLBCL." (PMID 23861822, 2013). "Here we compared the immunogenicity of Primary Effusion Lymphoma (PEL) cell death induced by anticancer drug Bortezomib (Velcade) and Tyrphostin AG 490, a Janus Activated Kinase 2/signal trasducer and activator of transcription-3 (JAK2/STAT3) inhibitor." (PMID 22412839, 2012). "Owing to the importance of JAK2/STAT pathway in hematological malignancies, and recurrent aberrations of JAK2 in several types of lymphoma, especially T-cell lymphoma, we hypothesized that GM-CSF might induce disease progression of ENKTL via JAK/STAT/PD-L1 axis." (PMID 34051805, 2021). "In our cases series, a patient treated with JAK2 inhibitor, indeed, developed MZL; however, it should be noted that this patient's exposure to anti-TNF (tumor necrosis factor) agents for her ankylosing spondylitis could have also contributed to her lymphoma." (PMID 31781224, 2019).
chronic myeloid leukemia (52 papers, 2010 to 2026). "Given the success of kinase inhibitors in the treatment of chronic myeloid leukemia, the discovery of activating JAK2 point mutations and JAK2 fusion genes in ALL, was a breakthrough for potential targeted therapies." (PMID 35903543, 2022). "Finally, we reported a case that illustrated the application of cdPCR in detecting low-allele burdens in a de novo chronic myeloid leukemia (CML) patient with a hidden JAK2 V617F subclone, which expanded during TKI treatment." (PMID 39043913, 2024). "Finally, a case report illustrated the application of cdPCR in detecting low-allele burdens in a de novo chronic myeloid leukemia (CML) patient with a hidden JAK2 V617F subclone, which expanded during tyrosine kinase inhibitor (TKI) treatment." (PMID 39043913, 2024). "Additionally, because Janus kinase 2 (JAK2) regulates BCR-ABL1 signaling in chronic myeloid leukemia, we decided to analyze the copy number of JAK2 gene." (PMID 33003326, 2020). "Only few case reports are available showing presence of JAK2 V617F mutation in chronic myeloid leukemia (CML)." (PMID 24639858, 2014). "Recent studies suggest that JAK2 serves as a novel therapeutic target in Bcr-Abl+ chronic myelogenous leukemia (CML)." (PMID 27551334, 2016). "Based on the success of tyrosine kinase inhibitors (TKIs) for the treatment of chronic myeloid leukemia (CML) and Ph+ ALL, there is potential for targeted JAK2 inhibitors to improve outcomes for patients with high-risk, JAK2-altered ALL." (PMID 35903543, 2022). "A standardized and validated approach to JAK2 VAF testing should be agreed and implemented, as has been successfully done for BCR-ABL1 in chronic myeloid leukemia." (PMID 41091181, 2025). "It’s been previously reported that the Janus kinase 2 (JAK2)/STAT5 pathway plays a crucial role in the survival and proliferation of chronic myeloid leukemia cells obtained from patients." (PMID 30979953, 2019). "Three JAK2-negative patients with elevated hemoglobin who tested positive for BCR/ABL1 fusion were diagnosed with chronic myeloid leukemia (CML) and excluded from further analysis." (PMID 36290845, 2022). "A previous study has reported that GM-CSF could induce resistance to imatinib and nilotinib in chronic myeloid leukemia (CML) via the activation of JAK2/STAT5, but didn’t mention the Immunological role of JAK2/STAT5 pathway in anti-tumor therapy." (PMID 34051805, 2021). "Moreover, in chronic myeloid leukemia blast cells, the long noncoding RNA MEG3 interacted with multiple proteins in a large complex comprising DNMT1, JAK2, TYK2, STAT3, and HDAC155." (PMID 32895373, 2020). "The majority of studies have focused on chronic myeloid leukemia (CML) and JAK2-mutant MPN." (PMID 31171568, 2019). "WP1130 prevents deubiquitination of a subset of kinases, such as Bcr-Abl in chronic myelogenous leukemia (CML), Janus-activated kinase 2 (Jak2), and autophagy-initiating kinase ULK1, resulting in their translocation to the aggresome, thus, failing to participate in signal transduction." (PMID 29039082, 2017). "These potentially include patients with fusions of JAK2 with PCM1, ETV6 and BCR, T-cell large granular lymphocytic leukaemia, chronic lympho-proliferative disorders of natural killer cells, Waldenstrom’s Macroglobulinaemia, chronic myeloid leukaemia and chronic lymphocytic leukaemia." (PMID 26131691, 2015). "Interestingly, JAK2 has been identified to be involved in two rare translocations: with ETV6, at 12p13, in acute lymphoblastic leukemia and rarely myeloproliferative (CML-like) disorder and with BCR, at 22q11.2, in patients with chronic myeloid leukemia." (PMID 22549126, 2012). "Unlike imatinib in chronic myeloid leukemia (CML), where already 6 months of TKI treatment can result in a durable clinical response by reduction of the BCR::ABL1 transcript, JAK2 inhibitor short-term treatment does not induce a significant reduction in MPN-driving allele burden." (PMID 39091915, 2024).
acute lymphoblastic leukemia (51 papers, 2010 to 2026). Leukemia with an acute onset, characterized by the presence of lymphoblasts in the bone marrow and the peripheral blood. "A t (p24: p13) leads to the generation of TEL::JAK2 fusion associated with the development of T-cell childhood acute lymphoblastic leukemia." (PMID 39091915, 2024). "Among these, gene rearrangements involving PCM1::JAK2 are rare and may present diagnostic challenges, particularly when manifesting as acute lymphoblastic leukemia (ALL)." (PMID 41530508, 2026). "The JAK2 R683G mutation located in the hinge region between N-terminal and C-terminal lobes of the pseudokinase domain, was identified in a screen of pediatric acute lymphoblastic leukemia (ALL) patient samples." (PMID 20585391, 2010). "Other JAK2 resistance-related mutations, such as G993A or L884P, have also been reported in cell models of acute lymphoblastic leukemia (ALL)." (PMID 35205715, 2022). "Ruxolitinib (rux) Phase II clinical trials are underway for the treatment of high-risk JAK2-rearranged (JAK2r) B-cell acute lymphoblastic leukemia (B-ALL)." (PMID 34376782, 2021). "JAK2 mutations have been associated with poor prognosis in pediatric B-cell precursor acute lymphoblastic leukemia (BCP-ALL)." (PMID 34680295, 2021). "Mutations in JAK1 and JAK3, as well as other rare mutations in JAK2, have been associated with T-cell acute lymphoblastic leukemia (T-ALL)." (PMID 32707925, 2020). "JAK2 mutations have also been identified in patients with acute lymphoblastic leukemia (ALL), AML, and acute megakaryoblastic leukemia (AMKL)." (PMID 30717771, 2019). "Finally, JAK2 activating mutations have been also reported in acute lymphoblastic leukemia." (PMID 26413812, 2015). "study, where in ATF7IP::JAK2 mediated acute lymphoblastic leukemia (ALL), CHZ-868 is potent against the ruxolitinib resistant variants such as Y931C and L983F." (PMID 39091915, 2024). "In clinical trials, the dual JAK2/3 inhibitor AG-490 significantly prevents B-cell growth in overcontrol in patients with acute lymphoblastic leukemia by preventing the inconsistent constitutive activation of JAK2." (PMID 36677654, 2023). "A heterogeneous genetic subtype of B-cell precursor acute lymphoblastic leukemia is driven by constitutive kinase-activation, including patients with JAK2 fusions." (PMID 34299194, 2021). "Down syndrome acute lymphoblastic leukemia (DS‐ALL) is characterized by high frequency of CRLF2‐rearrangements, JAK2‐mutations, or RAS‐pathway mutations." (PMID 33247204, 2021). "BBT594 and CHZ868, Type-II inhibitors of JAK2, illustrate satisfactory efficacy in preclinical MPNs and acute lymphoblastic leukemia (ALL) models." (PMID 28831147, 2017). "The detection and therapeutic targeting of MLL as well as JAK2 abnormalities in cases of ALL may be prognostically beneficial as they may represent a distinct subtype of acute lymphoblastic leukemia." (PMID 24274401, 2013). "This case pinpoints the fact that JAK2 rearrangements may play an important role in the pathogenesis of lymphoblastic leukemias." (PMID 24274401, 2013). "We describe a case of a patient who presented with B-cell acute lymphoblastic leukemia (B-ALL) with a JAK2 rearrangement." (PMID 41530508, 2026). "And studies have shown that JAK2 inhibitor TG101209 can inhibit T cell acute lymphoblastic leukemia (T-ALL) proliferation by inhibiting JAK/STAT pathway activation and regulating the interaction between apoptosis and autophagy." (PMID 36911202, 2023). "In 1996, a compound with JAK2 inhibitory activity was reported to inhibit acute lymphoblastic leukemia (ALL) cell growth: it was the first evidence of the role of JAKs as druggable targets." (PMID 32707925, 2020). "Although the underlying mechanisms were not shown, a recent study demonstrated that the USP9X inhibitor BRD0476 downregulated JAK2 signaling also in a subtype of acute lymphoblastic leukemia (ALL) that shows hyperactivation of JAK2 with or without the activating R683G mutation." (PMID 32050632, 2020).
acute lymphoblastic leukemia (continued). "Herein, we report a novel homozygous “G” deletion at exon 12 of the JAK2 gene in a pediatric patient with acute lymphoblastic leukemia (ALL)." (PMID 24744653, 2012). "Recurrent JAK2 fusion events involving diverse partner genes—including ATF7IP, EBF1, PAX5, SSBP2, RNPC3, GOLGA5, and PCM1—have been described in a subset of acute lymphoblastic leukemia cases." (PMID 41228238, 2025). "High-resolution breakpoint mapping by Optical Genome Mapping enables precise detection of clinically actionable gene rearrangements in acute lymphoblastic leukemia (ALL), including MEF2D::CSF1R and PAX5::JAK2 fusions—hallmarks of the Philadelphia-like (Ph-like) ALL subtype." (PMID 41228238, 2025). "This fusion tyrosine kinase can phosphorylate STAT5 directly and also lead to the activation of JAK2 in both CML and some forms of acute lymphoid leukemia (ALL)." (PMID 38611065, 2024). "JAK2 abnormalities may serve as target for precision medicines in pediatric B-cell precursor acute lymphoblastic leukemia (BCP-ALL)." (PMID 29163799, 2017). "Recent studies revealed that a substantial proportion of patients with high-risk B-cell precursor acute lymphoblastic leukemia (BCP-ALL) harbor fusions involving tyrosine kinase and cytokine receptors, such as ABL1, PDGFRB, JAK2 and CRLF2, which are targeted by tyrosine kinase inhibitors (TKIs)." (PMID 27176795, 2016). "The most representative example is BCR-ABL1-like acute lymphoblastic leukemia (ALL), which was first identified via hierarchical clustering of gene expression profile and a majority of them include gene fusions involving CRLF2, JAK2, and ABL gene categories." (PMID 34497767, 2021). "This fusion protein was characterized in T-cell acute lymphoblastic leukemia (T-ALL) patients, which constitutively activated JAK2 tyrosine kinase activity, STAT phosphorylation and conferred cytokine-independent T-ALL cell proliferation." (PMID 34680295, 2021).
liver cancer (49 papers, 2008 to 2025). An epithelial or non-epithelial malignant neoplasm that arises from the liver. "Our results suggest that the expression of JAK1 and JAK2 was associated with liver cancer progression and was also positively correlated with the severity of liver fibrosis." (PMID 35382859, 2022). "In this study, we found that enhanced JAK1 and JAK2 expression were associated with liver fibrosis/cirrhosis and liver cancer." (PMID 35382859, 2022). "The positive regulation of JAK2/STAT3 signaling pathways has also implicated in CD276-mediated epithelial-to-mesenchymal transition in liver cancer." (PMID 27329595, 2016). "It is reported that knockout of JAK2 increases apoptosis and impairs the proliferation of liver cancer, which is consistent with our results of the resected xenograft IHC, showing an increase in TUNEL‐positive cells and a decrease in Ki‐67‐positive cells." (PMID 39400496, 2025). "In liver cancer, it induces autophagy, while in CRC, the histone deacetylase inhibitor trichostatin A (TSA) reduces JAK2/STAT3 signaling, causing AK2/STAT3, leading to damage in 16HBE cells and contributing to asthma development." (PMID 40165005, 2025). "The deubiquitinase USP9x has been previously studied in several types of cancer including its involvement in the promotion of liver cancer through modulation of JAK2/STAT3 signaling." (PMID 39075050, 2024). "For instance, in liver cancer, F2R influences the efficacy of PD-1 immunotherapy through the JAK2/STAT1 signaling pathway." (PMID 39655193, 2024). "Further, the CucD-mediated downregulation of genes and proteins belonging to the PI3K/AKT/mTOR, MAPK, and JAK2/STAT3 cascades has been highlighted in liver cancer." (PMID 39770403, 2024). "For instance, interfered JAK2 was found to inhibit the proliferation of liver cancer cells, eventually reducing tumor size and weight." (PMID 38612844, 2024). "The activation of JAK2/STAT3 signaling pathway causes the reduction of the adriamycin-induced aging of cells, and obviously promotes liver cancer cells proliferation." (PMID 37716993, 2023). "More interestingly, we found that expression of JAK1 and JAK2 was positively correlated with the progression of liver cancer and the severity of liver fibrosis." (PMID 35382859, 2022). "The treatment of liver cancer cells with JAK2 inhibitor and IL-6 neutralizing antibody enhanced the adriamycin-induced aging of cells, and also significantly inhibited the proliferation rate of the cells." (PMID 36591515, 2022). "Immunohistochemistry staining of JAK1 and JAK2 were performed on liver tissue in mice with hepatic fibrosis and human liver tissue microarray of liver cirrhosis and liver cancer." (PMID 35382859, 2022). "JAK1 and JAK2 expression were markedly higher in liver cirrhosis tissues (n = 22), while highest in liver cancer tissues (n = 53) compared to normal liver tissues (n = 5)." (PMID 35382859, 2022). "Taken together, QE inhibited the progression of liver cancer, at least partially, by inhibiting the activation of JAK2/STAT3 signaling pathways." (PMID 31273958, 2019). "Taken together, these results showed that the proliferation, sphere formation and migration capacities of CD90+ liver cancer cells involved activation of IL6/JAK2/STAT3 signalling through the SHH/Gli pathway." (PMID 29722127, 2018). "We also further verified that IL6/JAK2/STAT3 signalling functions downstream of the SHH/Gli pathway in liver cancer stem cells." (PMID 29722127, 2018). "In gastric and liver cancers, miR-375 functions through the JAK2/STAT3 signaling pathway to control cell proliferation and apoptosis." (PMID 28186962, 2017). "Recently, a report demonstrating that PRL contributed to the proliferation of liver cancer cells via JAK2 signaling was published." (PMID 27102295, 2016).